ENSG00000287999 (novel transcript)
Gene: Long non-coding RNA gene on chromosome 4 (52,252,820 to 52,551,648, reverse strand). Ensembl gene ENSG00000287999.
Gene Ontology:
Biological process: RNA processing
Cellular component: nucleolus